LGALS1 (galectin 1)
Diseases named in the same sentence as LGALS1 in open-access papers (continued):
Sharing a sentence is not in itself a finding about the gene and the disease.
pancreatic ductal adenocarcinoma (8 papers, 2010 to 2023). An infiltrating adenocarcinoma that arises from the epithelial cells of the pancreas. "Galectin-1, a salient member of the galectin family, has been identified as a vital modulator of multiple signaling pathways contributing to the progression of pancreatic ductal adenocarcinoma." (PMID 37958483, 2023). "LGALS1, a glycan-binding protein, regulates tumor cell proliferation, invasion, and metastasis in pancreatic ductal adenocarcinoma." (PMID 35180865, 2022). "Galectin-1 has previously been shown to be strongly expressed in activated pancreatic stellate cells (PSCs) and promote the development and metastasis of pancreatic ductal adenocarcinoma (PDAC)." (PMID 29156810, 2017). "Gene expression profiling of pancreatic ductal carcinomas indicated that Galectin-1 is one of most highly expressed genes in PDAC." (PMID 24595374, 2014). "The proteomic analysis of pancreatic ductal adenocarcinoma compared to normal tissue demonstrates that galectin-1 expression was highly correlated to tumor histology and stage." (PMID 23658855, 2010). "Galectin-1 is a multifunctional target during Pancreatic ductal adenocarcinoma progression." (PMID 36712844, 2022). "Galectin-1, a member of carbohydrate-binding proteins with a polyvalent function on tumor progression, was found strongly expressed in pancreatic satellite cells (PSCs), which partner in crime with cancer cells and promote the development of pancreatic ductal adenocarcinoma (PDAC)." (PMID 24595374, 2014).
acute myocardial infarction (7 papers, 2014 to 2025). Necrosis of the myocardium, as a result of interruption of the blood supply to the area. "Galectin-1 deficiency increased cardiac infiltration of T cells, macrophages, and NK cells, but reduced recruitment of anti-inflammatory Treg cells, indicating that galectin-1 regulates Treg-mediated protection during acute myocardial infarction." (PMID 36873388, 2023). "Although galectin-1 is detected in normal heart tissues including cardiomyocytes, its level is strongly increased during acute myocardial infarction." (PMID 36873388, 2023). "Elevated galectin-1 expression influences the resolution of inflammation at later steps of acute myocardial infarction by restoring tissue homeostasis." (PMID 36873388, 2023). "Studies of galectin-1 have previously indicated altered regulation in both cerebral stroke, myocardial infarction, and congestive heart failure." (PMID 36295832, 2022). "Galectin-1, a β-galactoside-binding lectin mediating inflammation and neovascularization, is reported to attenuate ventricular remodeling after myocardial infarction." (PMID 33244142, 2020). "However, these protective effects appear to depend on the pathogenesis of the thrombotic disease as an opposite therapeutic effect of galectin-1 treatment was observed in a mouse model of acute myocardial infarction." (PMID 36873388, 2023). "Besides, the treatment of mice with recombinant Galectin-1 attenuated cardiac damage by preventing cardiac inflammation in a mouse model of acute myocardial infarction." (PMID 33435991, 2021). "Galectin-1, a glycan-binding protein primarily involved within the anti-inflammatory cardiac tissue response to acute myocardial infarction, has been shown to restrict vSMC motility and modulates focal adhesion turnover on fibronectin, via in vitro assays using galectin-1 knockout mouse SMCs." (PMID 31214600, 2019). "Taken with its effects on increasing SMC proliferation and restricting SMC motility, galectin-1 presents as a potential supplement for cardiac therapeutics post-myocardial infarction and a serum biomarker for cardiac stress with a well-characterized mouse model for in vivo evaluations." (PMID 31214600, 2019). "Galectin-1 levels in ng/mg of total protein at different time points post myocardial infarction." (PMID 24498007, 2014).
diabetic retinopathy (7 papers, 2015 to 2025). "Galectin‐1/LGALS1 is a hypoxia‐induced angiogenic factor associated with diabetic retinopathy (DR)." (PMID 31328390, 2019). "There have been several reports on direct and indirect interactions of galectin-1 in VEGF-signalling which make galectin-1 an interesting protein to study in the pathophysiology behind diabetic retinopathy." (PMID 36295832, 2022). "Taken together, there are substantial data pointing to a role of galectin-1 in diabetic retinopathy, with promising experimental studies indicating a possible therapeutic potential beside currently available treatment alternatives." (PMID 36295832, 2022). "Galectin-1 levels have also been reported to increase in the vitreous fluid, alongside the progression of diabetic retinopathy in humans." (PMID 36295832, 2022). "A study on patients with diabetic retinopathy tested the interaction between galectin-1 and the anti-VEGF treatment Aflibercept." (PMID 36295832, 2022). "The study also demonstrates a direct binding interaction between galectin-1 and Aflibercept, providing insight into a molecular signalling pathway for galectin-1 in diabetic retinopathy." (PMID 36295832, 2022). "Galectin‐1/LGALS1, a newly recognized angiogenic factor, contributes to the pathogenesis of diabetic retinopathy (DR)." (PMID 32150332, 2020). "The present study revealed several important findings on the hypoxia-unrelated induction of galectin-1 selectively in the pathogenesis of DR but not non-diabetic retinopathies." (PMID 29170525, 2017). "Lastly, our present findings revealed an additional anti-angiogenic role of aflibercept in neutralizing galectin-1, a non-VEGF family angiogenic factor associated with human diabetic retinopathy." (PMID 26648523, 2015). "In contrast, a previous study found elevated galectin-1 in diabetic retinopathy but not in RVO, suggesting that inflammation triggered by advanced glycation end products is the inducer of galectin-1 specifically in diabetic retinopathy." (PMID 39825912, 2025).
HIV-1 infection (7 papers, 2010 to 2025). The type species of lentivirus and the etiologic agent of acquired immunodeficiency syndrome (AIDS). "Galectin-1 is known to interact with gp120 and facilitate rapid HIV-1 infection of susceptible cells." (PMID 29093555, 2017). "Galectin-1 is a β-galactoside-binding protein family member, and it plays a critical role in Human Immunodeficiency Virus type 1 (HIV-1) infection in the human host." (PMID 39744515, 2025). "Sato and colleagues demonstrated that galectin-1 can promote HIV-1 infection of human T cells and macrophages by promoting viral adsorption to the target cells." (PMID 24995007, 2014). "However, these molecules may affect HIV-1 infection in an opposite way as some, such as mannose-binding lectin (MBL) and langerin, inhibit HIV-1 infection, while others, such as galectin-1, DC-SIGN, mannose receptor, syndecan-3 and DCIR, increase the susceptibility to HIV-1 infection." (PMID 24330394, 2013). "Galectin-1, a dimeric beta-galactoside-binding protein which acts as a soluble adhesion molecule by facilitating attachment of HIV-1 to the cell surface and facilitates HIV-1 infection by promoting early events of the virus replication cycle (i.e. adsorption)." (PMID 20849641, 2010). "Therefore, HIV-1 infection requires the assistance from various host adhesion molecules or receptors, such as dendritic cell (DC)-specific intercellular adhesion molecule 3-grabbing non-integrin binding receptor (DC-SIGN) and galectin-1." (PMID 32485969, 2020).
Hyperglycemia (7 papers, 2012 to 2025). An increased concentration of glucose in the blood. "Other factors that have recently been reported to induce PSC activation (as assessed by proliferation, migration, collagen production, αSMA expression or cytokine expression) include hyperglycaemia, endothelin 1, COX-2, galectin 1 and fibrinogen." (PMID 22973234, 2012).
influenza infection (7 papers, 2014 to 2023). "We demonstrated that genetic variations in lectin, galactoside-binding, soluble, 1 (LGALS1, also known as Galectin 1) are contributable to the differential susceptibility to A(H7N9) influenza." (PMID 25687228, 2015). "Moreover, the LGALS1-knockout mice were more susceptible to the fatal influenza infection than wild-type mice." (PMID 25687228, 2015). "Moreover, intranasal administration of recombinant galectin-1 during influenza virus infection reduced viral load and accompanying inflammation, tissue damage, and mortality in the murine model, and galectin-1 null mice were more susceptible to influenza infection than wildtype mice." (PMID 24995007, 2014). "We have previously shown that galectin-1 directly binds to the surface of intact influenza virions and inhibits viral infection in vitro and in vivo." (PMID 36823664, 2023). "We have reported that galectin-1 is upregulated during influenza infection, and recombinant galectin-1 proteins can bind to the virus and ameliorate IAV pathogenesis." (PMID 36823664, 2023). "Accordingly, influenza infection led to poorer survival rates in LGALS1 KO mice than in wild-type mice." (PMID 35632759, 2022). "Taken together, our findings indicate a potentially positive effect of Gal-1 treatment on ameliorating the progress of H1N1pdm09-induced acute lung injury and recombinant galectin-1 might serve as a new agent in treating influenza." (PMID 32595629, 2020). "Furthermore, a study with a mouse model of pneumococcal pneumonia after influenza has shown that galectin-1 and, in particular, galectin-3 expressed and secreted in the airway epithelial cells upon IAV infection bind strongly to IAV and Streptococcus pneumoniae." (PMID 36823664, 2023). "Although one study has demonstrated that rs4820294 and rs13057866 in LGALS1 are associated with higher expression of Gal1 protein in human cells and decreased susceptibility to influenza infection, there are few/no studies showing an association between LGALS1 genetic variants and Gal1 serum levels." (PMID 35806182, 2022).
osteoarthritis (7 papers, 2006 to 2025). A noninflammatory degenerative joint disease occurring chiefly in older persons, characterized by degeneration of the articular cartilage, hypertrophy of bone at the margins and changes in the synovial membrane. "In addition, LGALS1—also increased when TDM is incorporated—is proinflammatory in osteoarthritis via activation of the NF-κB pathway." (PMID 40224957, 2025). "A comparison of mRNA in bone expression in individuals with proximal femoral neck fractures (OP) or osteoarthritis with individuals without such issues, as well as a comparison with other genes, including LGALS1, verified less expression in OP patients." (PMID 38099525, 2024). "Equine BMSCs express high levels of galectin-1 mRNA relative to other articular cell types; however, BMSC galectin mRNA expression is diminished in the presence of pro-inflammatory cytokines prevalent in osteoarthritis (IL-1β and TNF-α)." (PMID 29096716, 2017). "Interestingly, Galectin-3 and its binding protein, but not Galectin-1, were reported to be elevated in RA but not in osteoarthritis." (PMID 16507131, 2006).
renal cell carcinoma (7 papers, 2014 to 2026). "The expression of galectin-1 (Gal-1) is associated with the migration and invasion of renal cell carcinoma (ccRCC) cells through the HIF-1α–mTOR signaling axis." (PMID 38965615, 2024). "In terms of the shared molecular mechanisms underlying periodontitis and renal cell carcinoma, six genes (IKZF1, LGALS1, LSP1, MNDA, VIM and WAS) were consistently upregulated in both disease tissues, indicating their potential involvement in the common pathogenesis of the two diseases." (PMID 42157182, 2026).
endometrial cancer (6 papers, 2011 to 2022). Primary or metastatic malignant neoplasm involving the endometrium (mucous membrane that lines the endometrial cavity). "Furthermore, multiple studies have indicated that galectin-1, a homodimeric protein involved in angiogenesis and cross-linking receptors, and galectin-3, a chimaera-type protein associated with cancer metastasis and inflammatory regulation, are mainly involved in endometrial cancer." (PMID 36578551, 2022). "In addition, galectin-1 immunoreaction was positively proportional to endometrial cancer grade, increasing from G1 to G3." (PMID 36578551, 2022). "In human endometrial cancers, the expression of galectin-1 is upregulated in uterine adenocarcinomas compared with normal adjacent endometrium, whereas expression of galectin-3 is downregulated in endometrial cancer cells compared with normal mucosa." (PMID 29389859, 2018). "Calb1 and galectin-1 are two putative MTDH downstream genes that may regulate the metabolism of phosphatidylinositol, which is part of the PI3K/AKT signaling pathway commonly upregulated in endometrial cancer." (PMID 21687633, 2011). "To our knowledge, this is the first paper to describe the presence of PD-L1 and PD-L2 in endometrial cancer as such, and we are not aware that any of the currently described molecules have been described in uterine sarcoma so far, except for possibly IDO, galectin-1 and galectin-3." (PMID 24658839, 2014).
gastric adenocarcinoma (6 papers, 2013 to 2025). "This scenario prompted us to investigate the relationship between the gene and protein expression of annexin-A1 (ANXA1/AnxA1) and galectin-1 (LGALS1/Gal-1) in an inflammatory gastric lesion as chronic gastritis (CG) and gastric adenocarcinoma (GA) and its association with H. pylori infection." (PMID 23431236, 2013).
head and neck squamous cell carcinoma (6 papers, 2014 to 2023). A squamous cell carcinoma that arises from any of the following anatomic sites: lip and oral cavity, nasal cavity, paranasal sinuses, pharynx, larynx, and salivary glands. "Galectin-1 is a hypoxia-regulated protein and a prognostic marker in head and neck squamous cell carcinomas (HNSCC)." (PMID 29232825, 2017). "In solid tumors, expression of galectin-1 was inversely correlated with the numbers of CD3+ T cells in tumor sections from patients with head and neck squamous cell carcinoma, and the expression of galectin-1 and CD3 also served as predictors for the prognosis of such patients." (PMID 29389859, 2018).
liver cancer (6 papers, 2022 to 2025). An epithelial or non-epithelial malignant neoplasm that arises from the liver. "In this study, we observed that CDDP resistance of liver cancer is due to CDDP-induced activation of JNK/c-Jun-ATF2/Galectin-1." (PMID 37215991, 2023). "Taken together, this work revealed that JNK/c-Jun-ATF2/Galectin-1 is a valuable target to overcome CDDP resistance in liver cancer and proposed a feasible approach to trace JNK activity in vivo." (PMID 37215991, 2023). "Mechanistically, the highly activated JNK phosphorylated c-Jun and ATF2 formed a heterodimer to upregulate the expression of Galectin-1, leading to promoting cisplatin resistance in liver cancer." (PMID 37215991, 2023). "In summary, this work confirmed that the high activity of JNK/c-Jun-ATF2/Galectin-1 mediates cisplatin resistance in liver cancer." (PMID 37215991, 2023). "And then, we investigated how Galectin-1 interfered with the therapeutic efficacy of CDDP treatment in liver cancer." (PMID 37215991, 2023). "Our findings revealed that JNK/c-Jun-ATF2/Galectin-1 is a potential target to reverse CDDP resistance in liver cancer." (PMID 37215991, 2023). "In liver cancer, Galectin-1 has been considered a bifunctional regulator of cell adhesion, polarization and growth." (PMID 37215991, 2023). "To verify the clinical relevance of our results, we analyzed the association of Galectin-1 with the clinical parameters of patients with liver cancer and observed that Galectin-1 expression was markedly upregulated in liver tissues compared with normal tissues." (PMID 37433225, 2023). "In short, inhibition of Galectin-1 reversed CDDP resistance in liver cancer cells." (PMID 37215991, 2023). "In general, JNK/c-Jun-ATF2 upregulated the expression of Galectin-1 in liver cancer cells." (PMID 37215991, 2023). "Moreover, the Galectin-1 inhibitor combined with sorafenib was used in the treatment of liver cancer." (PMID 36712844, 2022). "In this regard, galectin-1, identified by our proteomic analysis, was previously reported to be a direct target of miR-22 in vitro and to represent an important oncogene promoting liver cancer." (PMID 36139435, 2022). "Discovered in 1992 within the cDNA library of human liver cancer cell HepG2, LGALS2 is positioned on the opposite strand of the same chromosome as LGALS1, approximately 50 kb away." (PMID 40134029, 2025). "JNK/c-Jun-ATF2 was found to mediate CDDP resistance through upregulating Galectin-1, which promoted DNA damage repair to enhance tumor CDDP resistance in liver cancer." (PMID 37215991, 2023). "In addition, the mRNA levels of Galectin-1 were significantly increased after co-transfection of C2/c-Jun and C2/ATF2 in liver cancer cells." (PMID 37215991, 2023).
pulmonary fibrosis (6 papers, 2017 to 2024). Chronic progressive interstitial lung disorder characterized by the replacement of the lung tissue by connective tissue, leading to progressive dyspnea, respiratory failure, or right heart failure. "Galectin-1 inhibition increased apoptosis in the fibrotic lungs and attenuated lung function decline associated with hypoxia-induced pulmonary fibrosis (PF)." (PMID 28417017, 2017). "OTX008, a small molecule galectin-1 inhibitor previously shown to inhibit pulmonary fibrosis, inhibited TGFβ-induced fibroblast-to-myofibroblast transition." (PMID 39383242, 2024). "Galectin-1 transcript levels increase in the lungs of IPF patients, and although the biological significance of the galectin-1/MUC16 interaction is not fully understood, galectin-1 has been reported to promote the development of hypoxia-induced pulmonary fibrosis." (PMID 31514468, 2019).
viral infection (6 papers, 2010 to 2022). "Galectin-1, an animal lectin ubiquitously expressed in mammalian tissues, is reported to play important roles in viral diseases." (PMID 32595629, 2020). "Because of its particular binding specificity for galactosides, galectin-1 recognizes the surface envelope proteins of many human viruses and therefore is involved in viral infection." (PMID 25642837, 2015). "During viral infection, endothelial cells become activated and release immune mediators, including galectin-1." (PMID 20657665, 2010). "In addition to galectin-1, the role of galectin-3 in viral infection has been elucidated by several studies." (PMID 25642837, 2015). "Recent reports have revealed that galectin-1 can be upregulated by bacteria or virus infection." (PMID 25706563, 2015). "Although this process relies primarily upon interaction between viruses and cell surface receptors, soluble factors may also influence the binding of EV71 to host cells.Galectin-1 has been reported to participate in several virus infections, but is not addressed in EV71." (PMID 25706563, 2015).
breast tumors (5 papers, 2014 to 2023). "Our results demonstrate that galectin-1 can inhibit proliferation und metabolic cell activity and induce apoptosis in breast tumor cell lines with high expression levels of the Thomsen-Friedenreich (TF) antigen in monolayer and spheroid cell culture models." (PMID 27825375, 2016).